HLA-DRB1 (major histocompatibility complex, class II, DR beta 1)
Diseases named in the same sentence as HLA-DRB1 in open-access papers (continued):
Sharing a sentence is not in itself a finding about the gene and the disease.
multiple sclerosis (continued). "Specifically, the TF with the highest weight in the TF-expression model (β = 0.23 in muscle and β = 0.18 in blood) is CIITA, where variability in the CIITA gene has been reported to interact with specific mutations of HLA-DRB1 to increase the risk for multiple sclerosis and type 1 diabetes." (PMID 35627314, 2022). "Interestingly, the most prominently down-regulated vitamin D target gene of the HLA family, HLA-DRB1, is known as the major risk gene for multiple sclerosis." (PMID 35055093, 2022). "In addition, the HLA-DRB1*04:01/*04:04 genotypes are risk alleles (odds ratios are ∼4.14 and ∼3.17, respectively) for RA and the HLA-DRB1*15:01-DRB5*01:01 haplotype (up to 60% among Caucasians) is linked to multiple sclerosis (MS)." (PMID 35967436, 2022). "Variants in HLA-DRB1 have been associated with multiple sclerosis." (PMID 34624066, 2021). "A recent study of HLA-DRB1 class II molecules in multiple sclerosis, suggested that HLA variants might act in trans to compensate for the effect of risk variants." (PMID 34335681, 2021). "Finally, the leprosy risk allele HLA-DRB1*15:01 was a major risk factor for multiple sclerosis in earlier studies and has been associated with risk for UC and Parkinson’s disease." (PMID 32776973, 2020). "The HLA-DRB1*15 allele is a hallmark susceptibility locus for MS, which is marked by rs3135388." (PMID 27812365, 2016). "Infection with Epstein-Barr virus (EBV) and HLA-DRB1*1501-positivity is a risk factor for multiple sclerosis (MS), but whether an interaction between these two factors causes MS is unclear." (PMID 26656273, 2015). "HLA-DRB1*1501 allele are strongly associated with multiple sclerosis in African-American." (PMID 24359316, 2013). "It is often associated with multiple sclerosis, and both conditions are linked to HLA-DRB1*15." (PMID 23378732, 2013). "Second, both HLA-DRB1*15:01 and DQB1*06:02 have been previously implicated in brain autoimmune and infectious diseases such as multiple sclerosis, narcolepsy, and influenza-A7,9,10." (PMID 38503741, 2024). "For example, the risk of RA is strongly associated with HLA-DRB1*0401 in European ancestries and HLA-DRB1*0405 in East Asian ancestries; and HLA-DRB1*1501 has been associated with multiple sclerosis (MS)." (PMID 36980846, 2023). "HLA-DRB1 is one of the most upregulated genes in multiple sclerosis, having a special role in inducing demyelination." (PMID 35492305, 2022). "HLA-DRB1*0401-restricted MBP 111–129-specific Humanized TCP transgenic mice emulating multiple sclerosis (MS) presented dysphagia induced by restriction in mandible and tongue movement." (PMID 34067192, 2021). "Examples of associations between certain HLA types and autoimmune disease include HLA-B*27 and spondyloarthritis (SpA), HLA-B*51 and Behcet’s disease, and HLA-DRB1*15:01 and multiple sclerosis." (PMID 30772894, 2020). "Three HLA alleles had evidence for association with depression after correcting for multiple testing (p < .004): HLA-B*08:01 and HLA-DQB1*02:01 (SLE) and HLA-DRB1*03:01 (multiple sclerosis, primary adrenocortical insufficiency, SLE)." (PMID 31570195, 2020). "A differential methylation signal with a peak at HLA-DRB1 was observed in CD4+ T cells of multiple sclerosis patients compared with controls in another study, suggesting a potential explanation for this observation." (PMID 28270189, 2017). "Sequencing of the HLA-DRB1 promoter region in 156 subjects of Sardinian descent (112 healthy individuals and 44 multiple sclerosis affected individuals) carrying HLA-DRB1-DQA1-DQB1 haplotypes." (PMID 22848563, 2012). "Several HLA genes that play a major role in the immune response (including HLA-B/C, HLA-DRB1, and HLA-DRB5) were associated with 2 or more regional volumes and simultaneously with demyelinating diseases, including multiple sclerosis, a prominent immune-mediated disorder." (PMID 39269986, 2024).
multiple sclerosis (continued). "It is interesting to note that, in a disease with immunological similarities with IPF like multiple sclerosis, the association of persistent EBV in B cells with the presence of the HLA-DRB1-15:01 class II allele is an important risk factor for the development of the disease." (PMID 39464888, 2024). "For Multiple Sclerosis, an autoimmune condition, differential methylation in multiple HLA-DR loci in the blood reflects this fact, being corroborated by the increased expression of HLA-DRB1 and HLA-DRB5 in the brain of Multiple Sclerosis patients." (PMID 39060467, 2024). "Moreover, HLA-DRB1 has been reported to be related to the DNA methylation of multiple autoimmune diseases including Crohn’s disease, multiple sclerosis, SLE, and TID." (PMID 34539625, 2021). "Multiple sclerosis may originate in some cases by cross-recognition of EBV-specific T cells with an epitope in myelin basic protein (MBP) restricted by HLA-DRB1*1501." (PMID 26270649, 2015). "Genotype frequencies of the EBF1 polymorphism in HLA-DRB1*1501 positive and negative multiple sclerosis patients." (PMID 16255771, 2005). "The fourth most cited study, “Mapping Multiple Sclerosis Susceptibility to the HLA-DR Locus in African Americans”, was one of the first to examine MS genetics outside European populations, demonstrating that HLA-DRB1 (not DQB1) is the primary risk gene in African Americans." (PMID 40134718, 2025). "Differentially methylated regions in HLA-DRB1 were observed in CD4+ and CD8+ T cells purified from peripheral blood of 94 women with multiple sclerosis and 94 healthy women, and differential gene expression for HLA-DRB1 gene was detected in whole blood." (PMID 34539625, 2021). "They show that hypomethylation of the HLA-DRB1 promoter, which leads to higher expression of HLA-DRB1, is involved in the pathogenesis of for example multiple sclerosis." (PMID 34484204, 2021). "Elevated expression of the same HLA-DRB1 and -DRB5 probes from the same platform utilized in the present study reflected presence of a specific HLA haplotype in a study of multiple sclerosis." (PMID 25671313, 2015). "For example, DRB1*15:01–DRB5*01:01–DQA1*01:02–DQB1*06:02 are overrepresented in patients with multiple sclerosis while HLA-DRB1*03, HLA-DRB1*15, and HLA-DRB1*04 are overrepresented in systemic lupus erythematosus (SLE) and dictate type of auto-antibodies and SLE symptoms." (PMID 37328773, 2023). "To do this, we computed EWAS models controlling for the effect of both the HLA-DRB1 risk haplotype and non-MHC SNPs identified in the 2019 International Multiple Sclerosis Genetics Consortium GWAS using a polygenic risk score (PRS)." (PMID 37628757, 2023). "Frequency of HLA-DRB1 alleles in patients with coexisting CNS demyelinating disease and autoimmune thyroid disease (AITD) in comparison to healthy individuals and multiple sclerosis (MS) patients without AITD." (PMID 28533776, 2017). "Transmission disequilibrium test of the not-transmitted parental haplotype in multiple sclerosis patients carrying (DR3+) or not carrying (DR3−) the HLA-DRB1*03∶01-*02∶01 haplotype." (PMID 23593151, 2013). "However, the lack of association of genotypes in rs17281647 as well as in rs1132200 with susceptibility to multiple sclerosis was found in both HLA-DRB1*15:01– and HLA-DRB1*15:01+ individuals (data not shown)." (PMID 28444502, 2017).
type 1 diabetes (68 papers, 2009 to 2025). "VKH has reportedly been associated with human leukocyte antigen (HLA) genotypes HLA-DRB1*0405, which are also disease susceptibility genes for both type 1 diabetes and Graves' disease in the Japanese population." (PMID 40026970, 2025). "Highly associated pathways such as KEGG "Type I Diabetes," "Antigen processing and presentation," and "Systemic lupus erythematosus" share several genes, particularly HLA class I and II paralogs (HLA-DRB1, HLA-DQB1, HLA-DQA1, HLA-B)." (PMID 39495786, 2024). "Type 1 diabetes predisposing human leukocyte antigen (HLA) alleles (i.e., HLA-DRB1, HLA-DQA1, and HLA-DQB1) were found in 14.3% of subjects." (PMID 35010780, 2022). "HLA-DRB1*03:01 was associated with the development of type 1 diabetes of the youth in a Pakistani population and is also associated with increased susceptibility to systemic lupus erythematosus with the production of anti-Ro and anti-La antibodies." (PMID 35008256, 2021). "In this study, HLA genotyping on the type 1 diabetes susceptibility loci HLA-DRB1, DQA1 and DQB1 was performed using a high-resolution next generation sequencing method." (PMID 34946827, 2021). "The frequency of HLA-DRB1 risk alleles for type 1 diabetes is significantly lower in patients with MODY." (PMID 28052112, 2017). "The aim of this study was to identify susceptible HLA-DRB1 alleles for type 1 diabetes in a Spanish youth population and to determine their frequency in a cohort of pediatric patients with a confirmed genetic diagnosis of MODY." (PMID 28052112, 2017). "In summary, the frequency of HLA-DRB1 risk alleles for type 1 diabetes is significantly lower in patients with MODY." (PMID 28052112, 2017). "The aim of this study was to determine the frequency of susceptible HLA-DRB1 alleles for type 1 diabetes in a cohort of pediatric patients with a confirmed genetic diagnosis of MODY." (PMID 28052112, 2017). "On the contrary, HLA typing is a well standardized technique in clinical practice, is available in most hospitals in Spain and is able to identify all HLA-DRB1 genotypes associated with type 1 diabetes." (PMID 28052112, 2017). "Note that the polymorphism of HLA-DRB1 is considered as a susceptible genetic marker for several autoimmune conditions and diseases, such as type I diabetes and dilated cardiomyopathy." (PMID 24603486, 2014). "The African-specific HLA-DRB1*03:02 allele, which is associated with protection for Type 1 diabetes, occurs on the HLA-DQA1*04:01-HLA-DQB1*04:02 haplotype and on no other HLA haplotype in our samples." (PMID 23398374, 2013). "The unique diversity of the African HLA region we have uncovered supports a specific and major role for HLA-DRB1 in HLA-DRB1*03 haplotype-associated Type 1 diabetes risk." (PMID 23398374, 2013). "Using the WTCCC type 1 diabetes data, we were able to accurately assess the risk of haplotypes spanning HLA-DRB1, HLA-DQA1 and HLA-DQB1." (PMID 23762245, 2013). "In contrast to Europeans, in whom the HLA-DRB1*09:01 allele is neutral for Type 1 diabetes risk, in our African American samples, it confers susceptibility (odds ratio 2.35, 95% CI 1.09–5.09)." (PMID 23398374, 2013). "In conclusion, given the differences in risk of Type 1 diabetes associated with HLA-DRB1*03 and HLA-DRB1*08 haplotypes, our results are consistent with the assumption that HLA-DRB1 is causal on the HLA-DRB1*03 haplotype." (PMID 23398374, 2013). "In Europeans, HLA-DRB1*15 confers greatest protection from Type 1 diabetes associated with the alleles HLA-DRB1*15:01 and HLA-DQB1*06:02." (PMID 23398374, 2013). "HLA-DQA1 alleles were also very strongly associated with Type 1 diabetes in African Americans, reflecting the strong linkage disequilibrium with highly disease-associated HLA-DRB1 and HLA-DQB1 alleles." (PMID 23398374, 2013). "The excess was attributable to the HLA-DRB1*15:03 allele, which is rarely observed in Europeans, and is less protective for Type 1 diabetes than HLA-DRB1*15:01 in Europeans." (PMID 23398374, 2013).
type 1 diabetes (continued). "Cis eQTLs of the HLA-DRB1 locus with other SNPs have previously been associated with Type 1 diabetes in liver tissue and with cholesterol levels in omental and subcutaneous fat suggesting differential regulation of this locus across different tissues." (PMID 22383892, 2012). "The MHC region at chromosomal position 6p21 encodes many genes (such as HLA-DQB1 and HLA-DRB1) that have been associated with type 1 diabetes by using the single-locus test." (PMID 21569557, 2011). "In analogy with the studies in diabetes type I, we speculate whether HLA susceptibility alleles (and especially HLA-DRB1*03) with time play a declining role whereas environmental or lifestyle factors could play an increasing role in the RPL pathogenesis." (PMID 36776871, 2023). "The same recommendation may apply to the high frequency of HLA-DRB1*03 found in our cohort as a possible risk factor allele of type 1 diabetes mellitus." (PMID 29298671, 2018). "In the European GWAS, Hammer and colleagues were able to achieve resolution of 4 digit classical HLA alleles and amino acids in HLA-DRB1 through imputation using the Type 1 diabetes genetics consortium (T1DGC) Immunochip/HLA reference panel, which is predominantly European." (PMID 29868224, 2017). "HLA-DR4, a common antigen of HLA-DRB1, has multiple subtypes that are strongly associated with risk of type 1 diabetes (T1D); however, some are risk neutral or resistant." (PMID 34153873, 2021). "The HLA-DRB1*15 allele, which, despite a frequency of 0.14 in African American control subjects that is consistent with Europeans, was more common than expected in our African American case subjects: 0.06 compared with ≤ 0.01 in European subjects with Type 1 diabetes." (PMID 23398374, 2013). "Positions 11 and 71 of HLA-DRB1 have also been postulated to influence risk of IBD, type 1 diabetes, MS, sarcoidosis, and visceral leishmaniasis." (PMID 36810251, 2023). "Other small studies have shown that in Scandinavian APS-1 patients, PAI seems to be associated with HLA-DRB1*03, alopecia with HLA-DRB1*04-DQB1*0302, and that HLA-DRB1*15-DQB1*0602 is apparently protective against type 1 diabetes." (PMID 36763264, 2023). "In particular, HLA-DRB1*03 and HLA-DRB1*04, known for their implication in autoimmune thyroiditis and type 1 diabetes, were found to be significantly associated with PA, supporting its autoimmune origin." (PMID 35458234, 2022). "Like type 1 diabetes, the strongest genetic risk factors for LADA are variation in the MHC class II genes HLA-DQB1 and HLA-DRB1; and the highest risk is conferred by the HLA haplotypes HLA-DRB1*04-DQB1*0302 (“DR4”) and HLA-DRB1*0301-DQB1*0201 (“DR3”)." (PMID 35846274, 2022). "Several studies from different populations, including Brazilians, showed that HLA-DRB1*03 and HLA-DRB1*04 are the most frequent alleles in patients with type 1 diabetes." (PMID 34362434, 2021). "A previous HLA study in Brazilian type 1 diabetes patients showed similar haplotypes frequencies for HLA-DRB1*03 and HLA-DRB1*04 as described in the Caucasian population." (PMID 34362434, 2021). "Combinations of the HLA-DRB1, -DQA1, and -DQB1 alleles strongly affect the risk of type 1 diabetes, and the highest risk genotype has an odds ratio of >16." (PMID 34946827, 2021). "Risk can be independently conferred by DQ and DR alleles: for instance, type 1 diabetes risk is independently associated with both DQ2.5/8 alleles (HLA-DQB1*0201/HLA-DQB1*0302) and DR3/4 alleles (HLA-DRB1*0301/ HLA-DRB1*0405, HLA-DRB1*0401)." (PMID 33262997, 2020). "It is beyond the scope of the current study to consider fine-mapping of the MHC region, and it is well established that the HLA-DQB1, HLA-DRB1, HLA-A and HLA-B genes are the primary determinants of the MHC risk in type 1 diabetes." (PMID 28983737, 2018). "The distribution of frequencies of the HLA-DRB1 genotypes was significantly different in MODY compared to patients with type 1 diabetes (p<0.001)." (PMID 28052112, 2017).
type 1 diabetes (continued). "Particular combinations of HLA-DRB1, -DQA1 and -DQB1 alleles can strongly increase or decrease the risk of type 1 diabetes." (PMID 28550517, 2017). "In contrast, HLA-DRB1*07:01-HLA-DQA1*03:01-HLA-DQB1*02:02, confers susceptibility to Type 1 diabetes (frequency 3.1% in cases, 0.8% in controls; odds ratio 5.28, 95% CI 1.77–15.81)." (PMID 23398374, 2013). "In our study, the strongest association signal originates in a protective haplotype tagged by rs9275596-C that carries HLA-DRB1*1501 and DQB1*602, also associated with protection against type I diabetes." (PMID 22737082, 2012). "Carriers of pathogenic variants had HLA-DRB1 risk alleles for autoimmune diabetes and clinical characteristics compatible with type 1 diabetes except for the absence of autoimmunity." (PMID 31365591, 2019). "According to the presence or absence of the susceptible HLA-DRB1 alleles for type 1 diabetes, we considered three different HLA-DRB1 genotypes: 0 risk alleles (no DR3 no DR4); 1 risk allele (DR3 or DR4); 2 risk alleles (DR3 and/or DR4)." (PMID 28052112, 2017). "If antibodies are positive and the patient has evident clinical features of autoimmune diabetes, the diagnosis would be type 1 diabetes and then, HLA-DRB1 genotyping could just confirm it." (PMID 28052112, 2017). "In a recent study in North West Ethiopia, GAD-negative diabetes patients had the HLA-DRB1*04, including the HLA-DRB1*15 alleles, and the HLA-DRB1*15 allele, which has also been shown in other populations to confer one of the strongest protection for type 1 diabetes." (PMID 36778553, 2023). "Although HLA-DRB1*15:03 is on the same haplotype, with HLA-DQB1*06:02, this African-specific haplotype could well have different sequences affecting class II gene expression or structure, that increase its predisposition to Type 1 diabetes." (PMID 23398374, 2013). "However, pregnancy-associated fulminant type 1 diabetes is distinguished by significantly lower arterial blood pH, elevated serum amylase levels, and significantly higher prevalence of the HLA-DRB1*09:01-DQB1*03:03 haplotype compared to non-pregnancy-associated fulminant type 1 diabetes." (PMID 40650275, 2025). "In cluster 2, the significantly enriched genes were HLA-B, HLA-A, HLA-DRB1, HLA-DQA1 and HLA-DQB1, with all genes related to allograft rejection, GVHD, type I diabetes, autoimmune thyroid disease and viral myocarditis." (PMID 37063831, 2023). "Both HLA-DRB1*15:01 and HLA-DRB1*15:03 were less protective for Type 1 diabetes in our African American samples [odds ratio 0.36 (95% CI 0.11–1.11), odds ratio 0.39, 95% CI 0.19–0.80)] than HLA-DRB1*15:01 in Europeans (odds ratio 0.05, 95% CI 0.04–0.07)." (PMID 23398374, 2013). "This was also reflected in the KEGG pathway analysis of trans-mQTLs where type 1 diabetes was found to be an enriched pathway of relevance in human pancreatic islets, including the following genes: PTPRN2, HLA-DRB1, HLA-B, HLA-C, HSPD1 and HLA-DRB5 (Padj = 6.0×10−4)." (PMID 25375650, 2014). "The difference in HLA-DRB1 genotype distribution between MODY and type 1 diabetes is especially remarkable when patients carry two risk alleles (5.4% MODY vs. 48.1% type 1 diabetes) or none (64.9% MODY vs. 7.5% type 1 diabetes)." (PMID 28052112, 2017). "This method could be used to replace HLA-DRB1 typing even though it cannot identify the DR3 and DR4 homozygous genotypes that also confer a remarkable risk to type 1 diabetes and it may not be accessible everywhere." (PMID 28052112, 2017). "We can only speculate on why PA is associated with a lower incidence of LADA only in individuals without genetic susceptibility to diabetes; the HLA-DRB1 and HLA-DQB1 genotypes are the main risk factors for β-cell autoimmunity and loss of β-cell function leading to type 1 diabetes." (PMID 32835373, 2020).
type 1 diabetes (continued). "To examine the validity of HLA-DRB1 genotyping in the selection of pediatric patients for genetic study of MODY, we categorized the groups as associated with MODY, when one or no risk alleles were present, and as associated with type 1 diabetes, when two risk alleles were present." (PMID 28052112, 2017).